INS (insulin)
Diseases named in the same sentence as INS in open-access papers (continued):
Sharing a sentence is not in itself a finding about the gene and the disease.
Insulin resistance (continued). "CFRD is primarily caused by pancreatic dysfunction that leads to insufficient insulin release and/or insulin resistance." (PMID 34836301, 2021). "By losing weight, women with obesity improve their metabolic- and cancer-related risk biomarkers, including insulin resistance and insulin-signaling adipokines, and circulating pro-inflammatory cytokines that promote tumorigenesis." (PMID 34960058, 2021). "T2DM is a multifactorial and polygenic disease caused by insulin resistance and impaired insulin secretion." (PMID 34441631, 2021). "The impact of infection-induced insulin insensitivity on the systemic metabolism highly resembles hyperglycemia and hyperlipidemia as hallmark states of chronic insulin resistance and cachexia." (PMID 33659253, 2021). "The onset of type 2 diabetes (T2D) is a consequence of the progressive loss of adequate β-cell insulin secretion, which frequently occurs under a background of insulin resistance." (PMID 33505497, 2021). "Breakfast consumption is significantly associated with lower BMI, body fat, insulin, homeostatic model assessment of insulin resistance (HOMA-IR), and MetS score, showing some gender differences." (PMID 33923450, 2021). "In contrast, accumulation of anti-inflammatory PPARγ positive macrophages (M2 macrophages) leads to improvements in AT inflammation and insulin sensitivity, while loss of macrophage PPARγ increases AT inflammation and insulin resistance." (PMID 34248937, 2021). "Over time, insulin resistance will cause an increase in fasting glucose and reduced insulin-mediated glucose clearance." (PMID 34576959, 2021). "The main pathogenesis of type 2 diabetes has been associated with peripheral insulin resistance and deficient insulin production due to the dysregulation of insulin secretion." (PMID 34880923, 2021). "The association between LETM1 methylation and fasting insulin levels suggests that it can serve as an epigenetic marker to indicate future development of insulin resistance and Type II diabetes in obese individuals." (PMID 33815143, 2021). "Among the markers of the insulin resistance of the fat loss group, the fasting insulin level was improved after the intervention, although HOMA_IR was increased." (PMID 33407104, 2021). "In this context, insulin resistance is defined as the decreased ability of a tissue to adequately respond to the actions of insulin, which is a risk factor for developing type-2 diabetes (T2D)." (PMID 33893069, 2021). "Decreased adiponectin is implicated in the development of insulin resistance, obesity, and type 2 diabetes, whereas its elevation improves insulin sensitivity and energy metabolism." (PMID 34960104, 2021). "The deficit in functions of insulin indicates a decline in insulin secretion (insulin secretion deficiency) or the case where the insulin function is adversely affected (insulin resistance)." (PMID 33390816, 2021). "In acromegaly, there is a decrease in the amount of fat mass and an increase in insulin resistance, and mice with the isolated GH deficiency are characterized by an increased sensitivity to insulin, despite the excess fat mass." (PMID 33586392, 2021). "Epidemiologic data indicate that HS is associated with insulin resistance, and HS provokes an impairment of insulin action in skeletal muscle." (PMID 34680557, 2021). "In summary, mitochondrial hypometabolism and oxidative stress are the factors that reduce SDH activity, thereby predisposing to less activation of the IR during insulin stimulation and resulting in the development of insulin resistance." (PMID 33810179, 2021). "In the Rotterdam study with 3139 participants, a higher risk of AD was associated with insulin levels and insulin resistance based on the HOMA-IR index, although only within 3 years from baseline and not after 3 years." (PMID 33402193, 2021). "While visceral obesity leads to a reduction in the glucose uptake pathway regulated through insulin and was associated with insulin resistance." (PMID 34867343, 2021).
Insulin resistance (continued). "The insulin level was significantly decreased in the fat loss group; however, the homeostasis model assessment method-insulin resistance (HOMA-IR) levels were significantly increased in both groups (Wilcoxon’s signed-rank test, P < 0.05)." (PMID 33407104, 2021). "In our previous reports, PAS was associated with higher SBP, higher percentage of DM, serum insulin levels, and homeostasis model assessment of insulin resistance in patients who underwent kidney transplantation." (PMID 34684048, 2021). "This association must be attributed to extremely severe insulin resistance as well as GH’s lipolytic action with an increase in free fatty acids and the suppression of insulin secretion." (PMID 33995272, 2021). "Recent studies indicate that exosomes produced by adipocytes from insulin-resistant subjects contain proteins that are strongly associated with insulin resistance and T2D, such as calreticulin, S100A6, mimecan, PARK7/DJ1, PPIB, and tenascin." (PMID 34299048, 2021). "Several lines of evidence show that the impairment of proximal insulin signaling causes insulin resistance in obesity and T2D." (PMID 33672754, 2021). "This choice is justified by the fact that insulin pulses contribute 60 to 85% of the total insulin secretion, and changes to this pattern have been associated with insulin resistance and type 2 diabetes (T2D)." (PMID 34206296, 2021). "The main pathophysiological causes of GDM are considered to be decreased insulin secretion and abnormal insulin resistance, which are associated with impaired fatty acid metabolism." (PMID 34130655, 2021). "TNF-alpha concentration is also linked with peripheral insulin resistance and elevated plasma glucose as well as insulin levels before the onset of type 2 diabetes." (PMID 34367469, 2021). "Resistin, PAI-I, and adiponectin are adipokines that are associated with insulin resistance/insulin sensitivity." (PMID 33705641, 2021). "The disruption of insulin signaling resulting in insulin resistance is also implicated in Preeclampsia (PE) associated placental endothelial dysfunction." (PMID 33504861, 2021). "In order to ensure a sufficient supply of the mammary gland with glucose, hormonal changes, such as reductions of insulin and the insulin-sensitizing hormone adiponectin, occur causing a status of insulin resistance." (PMID 34517929, 2021). "Excess exposure to insulin and hyperinsulinemia are thought to increase basal insulin signaling, which can contribute to insulin resistance and cause atherosclerosis." (PMID 34118892, 2021). "Palmitic acid contributes to the development of insulin resistance, while oleic acid protects cells from the attenuation of the insulin signaling pathway caused by palmitic acid." (PMID 33463892, 2021). "The risk of insulin resistance is reduced owing to a decrease in cellular oxidative stress and enhancement of insulin signaling and glucose transport." (PMID 34578858, 2021). "Insulin resistance is characterised by an impaired ability of the cells to use normal insulin concentrations and is associated with risk of developing type 2 diabetes and cardiovascular disease." (PMID 34143812, 2021). "African ancestry has also been reported to have high insulin levels in the blood, more insulin resistance, and a greater risk for type 2 diabetes than European ancestry." (PMID 34299261, 2021). "Several established studies have reported that impaired insulin activities and neuronal insulin resistance are associated with AD pathologies, while regulation of these factors prevents AD." (PMID 33849621, 2021). "On the other hand, immunologic or genetic loss of function resulted in a significant decrement in insulin and glucose levels, providing a protective mechanism against hyperinsulinemia and insulin resistance." (PMID 34419063, 2021). "It encodes some essential proteins related to insulin transduction and indeed plays a role in insulin resistance." (PMID 33691763, 2021).
Insulin resistance (continued). "It has been defined that brain insulin resistance occurs primarily with early hyperactivation of insulin signaling, including mTOR hyperactivity, which causes negative feedback on the insulin receptor, IRS1 and mTOR itself." (PMID 34065168, 2021). "As extension, the results showed that the present model of obesity is associated with insulin resistance and hyperinsulinemia as revealed with elevated TyG/reduced insulin sensitivity and increased fasting insulin concentration respectively." (PMID 34556775, 2021). "This study therefore supports the notion that the effects of autophagy on insulin sensitivity are mediated by the level of ER stress, and specifically that deficient autophagy promotes ER stress and subsequent insulin resistance." (PMID 34336862, 2021). "In muscles, insulin resistance is associated with impaired insulin action on glucose transport and glucose metabolism." (PMID 33708999, 2021). "EG poisoning can cause transient pancreatitis which results in reduction in serum insulin level; also an insulin resistance can be seen in association with acute renal failure which develops in EG poisoning within 24–72 h of exposure." (PMID 33672765, 2021). "Diseases related to impaired insulin signaling, commonly referred to as insulin resistance, are predominantly associated with altered metabolic function." (PMID 33845179, 2021). "Regarding cardiometabolic risk factors, levels of fasting insulin and insulin resistance improved in the weight loss group after intervention, but not in the weight gain group." (PMID 34202475, 2021). "Type 2 diabetes mellitus (T2DM) has become a major global public health concern and is caused by severe systemic insulin resistance and impaired insulin sensitivity." (PMID 34373742, 2021). "We assume that the elevated insulin levels are caused by insulin resistance (as in the metabolic syndrome) mainly in the muscles which would further disturb muscular metabolism." (PMID 33882940, 2021). "The relationship between insulin resistance and visceral adipose tissue mass is directly proportional, and weight loss has been reported to improve insulin sensitivity." (PMID 34442147, 2021). "Metabolic cascades of elevated lipid profiles, oxidative stress, insulin, and inflammatory biomarkers are implicated in insulin resistance progression." (PMID 34037093, 2021). "Independent of intervention group, we observed that a 10% or greater weight loss improves biomarkers of insulin sensitivity and insulin resistance." (PMID 34578984, 2021). "Hyperglycaemia is common and is probably caused by two effects of catecholamines, namely increased insulin resistance and inhibition of insulin secretion from beta cells." (PMID 34170845, 2021). "Adipose tissue insulin resistance has been associated with dysregulated insulin signaling, impaired glucose uptake, and lipid homeostasis." (PMID 34686659, 2021). "Overweight/obesity causes the development of insulin-resistance in peripheral tissues, which, in turn, increases even more the release of insulin." (PMID 33063272, 2021). "SGE also regulated glycometabolism in this NAFLD model by relieving insulin resistance, thereby causing a decrease in serum concentrations of insulin and glucose." (PMID 34441028, 2021). "Overall, the results of our gene expression study point to the upregulation of genes positively involved in insulin sensitivity, and the downregulation of genes implicated in insulin resistance, in the HPD offspring exposed to a metabolic challenge." (PMID 34069853, 2021). "Changes in adiposity have been shown to effect glucose metabolism and insulin sensitivity, e.g., visceral adipose tissue accumulation is associated with the development of insulin resistance." (PMID 34587168, 2021). "Although weight loss is associated with decreased insulin resistance, recent clinical results suggest that gastric bypass normalizes insulin sensitivity well before a significant reduction in body weight." (PMID 34673835, 2021).
Insulin resistance (continued). "While in type II diabetes mellitus individuals, have relative insulin deficiency and peripheral insulin resistance that require either oral medication or insulin/insulin analog or both." (PMID 34077431, 2021). "High fat diet causes insulin resistance in peripheral tissues due to lipotoxicity, while low dose of streptozotocin induces mild defect in insulin secretion." (PMID 33449943, 2021). "Increased adipose tissue is associated with insulin resistance and hyperinsulinemia, with raised circulating insulin enhancing colorectal epithelial cell proliferation in rat models." (PMID 34324486, 2021). "Considering that there is a significant association between endothelial dysfunction and insulin resistance, insulin sensitizers are anticipated to ameliorate endothelial function through restoring PI3-kinase/Akt/eNOS pathway and increasing NO production." (PMID 34439553, 2021). "The quantified CCC is associated with FBG, HbA1c, insulin, and insulin resistance index using cross-sectional analysis at the time of CT examination." (PMID 34966360, 2021). "DMTII is caused by the development of insulin resistance, meaning the inability of cells to respond to insulin due to a transmission blockage of the insulin receptor, mainly in muscle and liver cells." (PMID 34804028, 2021). "A recent retrospective analysis of a large cohort of T2D subjects has shown that insulin therapy is associated with a markedly increased risk of CA; this effect was partly attributed to insulin resistance." (PMID 35011813, 2021). "Our findings suggest that during adolescence, the prolonged insulin response in OVOB females is also associated with insulin resistance." (PMID 34684365, 2021). "Its M3 receptor antagonism causes an alteration in glucose control and insulin response, and the blockade of the H1 receptor favors the development of insulin resistance." (PMID 34335273, 2021). "Taken together, these findings suggest that insulin resistance and chronic low-grade inflammation are associated with a reduction in insulin sensitivity and increased levels of IL-1β." (PMID 34638553, 2021). "Subjects with adiponectin and AdipoR1 signaling deficiencies developed brain insulin resistance and impaired downstream insulin signaling, which mediates AD pathology." (PMID 33849621, 2021). "PPARγ agonists increase insulin sensitivity and ameliorate salt sensitivity, whereas deficiency of PPARγ results in severe insulin resistance and hypertension." (PMID 34966295, 2021). "Gut microbial profiling of individuals with insulin resistance and insulin sensitivity is associated with different host dietary intervention responses and weight changes." (PMID 35050149, 2021). "T2DM is associated with the development of insulin resistance by target organs and decreased insulin production from pancreatic beta cells." (PMID 34795728, 2021). "For example, insulin resistance is a risk factor for prostate cancer and, as adiponectin is an insulin-sensitising hormone, levels are lower in men with insulin resistance." (PMID 33431998, 2021). "Insulin resistance is also characterized by altered insulin signaling responses associated with impaired vasculature, increased acylcarnitine contents, altered amino acid availability, and diminished glucose uptake in skeletal muscle." (PMID 34959870, 2021). "While hypertension is less closely associated with insulin resistance than are other metabolic abnormalities 34, the antihypertensive treatment improves both insulin sensitivity and endothelial function." (PMID 34104095, 2021). "The excess visceral fat also causes insulin resistance as well as an increase in insulin levels, which decrease SHBG production in the liver, leading to higher levels of E2." (PMID 34940598, 2021). "Insulin resistance and deficiency are increased by abnormally creating insulin signaling through PI3K/Akt/GSK3-β signals; GSK3-β activation is an important component of NFT and can lead to hyperphosphorylated tau." (PMID 34489627, 2021).